CAPZA1 (capping actin protein of muscle Z-line subunit alpha 1)
Diseases named in the same sentence as CAPZA1 in open-access papers (continued):
Sharing a sentence is not in itself a finding about the gene and the disease.
tumor (16 papers, 2013 to 2026). "Given that metabolic and cytoskeletal dysregulation could be taken as a hallmark of ccRCC, CAPZA1 may influence lipid metabolic dysregulation-driven tumor progression or metastatic potential." (PMID 41354870, 2025). "The CAPZA1[T] variant binds hnRNP K and PTBP1 to stabilize its mRNA and inhibit tumor aggressiveness, whereas the CAPZA1[G] allele promotes UPF1-mediated mRNA decay and diminishes this protective effect." (PMID 41787560, 2026). "To assess the physiological significance of the LPE18:1/CAPZA1 axis in ccRCC pathogenesis, we established a xenograft tumor model through subcutaneous implantation of 786-O cells with stable CAPZA1 knockdown into nude mice." (PMID 41354870, 2025). "While the actin-capping function of CAPZA1 is well documented, its role in tumor metabolism is poorly understood." (PMID 41354870, 2025). "Histological analysis demonstrated that knockdown of CAPZA1 significantly inhibited tumor cell proliferation, lipid deposition, and ACAT2 expression in xenograft tumors, whereas OSS-128167 treatment further enhanced these inhibitory effects." (PMID 41354870, 2025). "Histopathological analysis of xenograft tumors revealed that LPE18:1 treatment alone significantly promoted tumor growth, whereas simultaneous CAPZA1 knockdown obviously attenuated LPE18:1-induced tumor progression." (PMID 41354870, 2025). "We conducted a comprehensive bioinformatic analysis to investigate the mRNA and protein expression levels of Tks4 and its associated partner molecules (CD2AP, GRB2, WASL, SRC, CTTN, and CAPZA1) across different tumor types." (PMID 39234565, 2024). "In normal tissues, RPL22L1, INHBA, and CAPZA1 were found to be significantly increased in CRC patients for whom experienced tumor lymphatic metastasis." (PMID 35909892, 2022). "During tumor progression, CAPZA1, GRB2, NF2EL3, PLEKHO1, SIGLEC1, and UBE2Z were expressed at higher levels in late-stage KIRC, whereas EMX2, FUCA1, IMPA2, and RORC were expressed at higher levels in early-stage KIRC." (PMID 35127943, 2022). "In conclusion, we demonstrated that miR-875-5p functions as a tumor-promoting gene via down-regulation of CAPZA1 in ESCC cells." (PMID 33505778, 2021). "The effect of CAPZA1 overexpression on tumor cell proliferation, migration and invasion was assessed in CAPZA1-overexpressing MKN-45 cells." (PMID 23545944, 2013). "We further utilized the starBase database to verify whether CAPZA1 expression is overexpressed in multiple tumor tissues." (PMID 36686785, 2022). "Similarly, CAPZA1 significantly inhibited intrahepatic metastases of HCC cells in an orthotopic transplantation tumour model." (PMID 28093067, 2017). "CAPZA1-OE correlated with smaller tumor size (3.7 cm) compared to CAPZA1-UE (4.8 cm) (p<0.01)." (PMID 23545944, 2013). "Results showed that CAPZA1 overexpression is associated with well differentiated histology, smaller tumor size, higher T1 stage, absence of LN metastasis, lower TNM stage, lower recurrence rate and longer survival." (PMID 23545944, 2013). "Similarly, this correlation had the same trend, indicating that CAPZA1 might serve as a new tumor immunotherapy response predictor in LUAD." (PMID 36686785, 2022). "Therefore, the purpose of this study was to determine whether miR-875-5p has a tumor-promoting function via down-regulation of CAPZA1 and if the SNP has the potential disrupt the binding of miR-875-5p to CAPZA1 in ESCC." (PMID 33505778, 2021).
tumor (continued). "Results showed that CAPZA1 overexpression in GC is associated with well differentiated histology, smaller tumor size, lower T stage, absence of lymph node (LN) metastasis, lower TNM stage, lower recurrence rate and longer survival time, compared to CAPZA1 underexpression." (PMID 23545944, 2013). "Biotin-RNA pulldown combined with mass spectrometry and RIP assays showed that CAPZA1[T] mRNA binds to hnRNP K and PTBP1, enhancing its stability and tumor-suppressive function." (PMID 41787560, 2026). "CAPZA1 depletion significantly inhibited tumor growth, and OSS-128167 treatment further suppressed tumor progression." (PMID 41354870, 2025). "Genetic or pharmacological inhibition of the CAPZA1/SIRT6 axis can reverse LPE18:1-induced lipid deposition and tumor progression in xenograft models." (PMID 41354870, 2025). "Clinically, CAPZA1 and SIRT6 levels correlate with advanced tumor stage and poor prognosis in ccRCC cohorts." (PMID 41354870, 2025). "Histomorphology analysis of xenograft tumor specimens revealed that LPE18:1 treatment significantly enhanced cell proliferation, whereas CAPZA1 knockdown effectively abrogated the LPE18:1-induced proliferative response." (PMID 41354870, 2025). "Taken together, these findings demonstrate that CAPZA1 plays a pivotal role in mediating LPE18:1-induced lipid accumulation and tumor progression in ccRCC." (PMID 41354870, 2025). "Consistently, the confusion matrix statistics showed that the normal and tumor samples can be reliably separated using gene expression data for CD2AP, GRB2, WASL, SRC, CTTN, CAPZA1, and Tks4 with 97% sensitivity and 80% specificity." (PMID 39234565, 2024). "CAPZA1, HLA-E, IMPA2, NFE2L3, PLEKHO1, SIGLEC1, and UBE2Z were expressed at higher levels in tumor tissues, whereas EMX2, FGL2, FUCA1, and GRB2 were expressed at lower levels in tumor tissues." (PMID 35127943, 2022). "Next, we need to validate the roles of CAPZA1 in LUAD on antitumor immunotherapy and tumor immunity based on more basic experiments." (PMID 36686785, 2022). "Thus, CAPZA1 could be a tumour biomarker to determine the prognosis of HCC patients." (PMID 28093067, 2017). "The effect of CAPZA1 depletion on tumor cell proliferation, migration and invasion was assessed in MKN-45 cells using CAPZA1-siRNA." (PMID 23545944, 2013). "We subsequently assessed lipid deposition in xenograft tumor tissues via Oil Red O staining and found that LPE18:1 treatment significantly promoted intracellular lipid accumulation, whereas concurrent CAPZA1 knockdown nearly completely abrogated LPE18:1-induced lipid deposition." (PMID 41354870, 2025). "Likewise the tumour specific expression of the RAGE binding proteins lectin, galactoside-binding, soluble, 3 and CAPZA1 in tumours of EGF transgenic mice is highly suggestive for a sustained crosstalk between RAGE and EGFR." (PMID 25872475, 2015). "Indeed, high CAPZA1 and AC026356.1 expression was significantly positively correlated with PD1, PD-L1, and CTLA-4 in LUAD, respectively, demonstrating that CAPZA1 can mediate tumorigenesis and progression by regulating tumor immune escape in LUAD." (PMID 36686785, 2022). "In addition, some groups discovered that hypoxia treatment also induced actin cytoskeleton remodeling by regulating the binding of CAPZA1 to F-actin, which further supports our observation that the SIM of LANA participates in the regulation of cell migration and tumor invasion in hypoxia." (PMID 34726485, 2021). "However, neither the role of CAPZA1 in HCC nor the molecular mechanism of CAPZA1 regulation of tumour metastasis has been defined." (PMID 28093067, 2017). "While CAPZA1, CAPZA2 and CAPZB, but not CAPZA3 levels correlated well with PIM1 levels in all tumor tissues, similar correlations were also observed for PIM2 and PIM3 in the samples with high Gleason scores." (PMID 32771000, 2020).
cancer (15 papers, 2013 to 2026). A tumor composed of atypical neoplastic, often pleomorphic cells that invade other tissues. "Lee et al21 found that CAPZA1 is a marker for a good prognosis in GC and is associated with the decreased migration and invasion of cancer cells." (PMID 31989722, 2020). "UBR5 overexpression could promote the degradation of CAPZA1 via the UPS and induce the accumulation of F-actin, which has been described as an essential molecular event during the process of CAPZA1 deficiency-induced cancer cells migration and invasion." (PMID 33777788, 2021). "In conclusion, CAPZA1 overexpression may be a suitable marker of good prognosis in GC and is associated in vitro with decreased cancer cell migration and invasion." (PMID 23545944, 2013). "SCFA-induced CAPZA1-overexpressing cells serve as a scaffold niche that supports CagA activity and promotes CD44v9-positive cancer stem-like cells." (PMID 41586340, 2026). "Our study findings show that SCFAs provide a foothold niche for epithelial cells for CagA stabilization and activity by generating CAPZA1-overexpressing cells and facilitating gastric epithelial cell transformation into CD44v9-positive cancer stem-like cells." (PMID 41586340, 2026). "In our research, we first found that CAPZA1 serves as an oncogene in pan-cancers from the TCGA data and higher CAPZA1 expression process unfavorably prognostic value in LUAD based on starBase database, PrognoScan, and LOGpc database." (PMID 36686785, 2022). "This current study investigated the expression profiling and prognostic value of CAPZA1 in pan-cancers based on several databases." (PMID 36686785, 2022). "For the first time, collectively, we comprehensively determine that CAPZA1 serves as an oncogene in pan-cancers and has a high CAPZA1 expression process that has an unfavorably high prognostic value in LUAD based on the starBase and PrognoScan databases." (PMID 36686785, 2022). "TME harbors comprehensively infiltrating immune cells, which contribute to influencing the development of cancers, so we investigated the relationship between CAPZA1 expression and immune infiltration." (PMID 36686785, 2022). "Previous studies have confirmed that CAPZA1 elicits pivotal roles in regulating the onset and development of human cancers." (PMID 36686785, 2022). "Firstly, the starBase database was employed to explore the prognosis of CAPZA1 in pan-cancer data downloaded from the TCGA." (PMID 36686785, 2022). "As expected, the mRNA levels of RPL22L1, INHBA, and CAPZA1 were significantly higher in cancer than in normal tissues; conversely, HMGCS2 was significantly downregulated in cancer." (PMID 35909892, 2022). "The regulation of F-actin remodeling has been described as an important mechanism by which CAPZA1 influenced cancer metastasis." (PMID 33777788, 2021). "CAPZA1-OE showed a significantly higher rate of T1- and T2-stage cancer (62.1 vs. 14.4%) than CAPZA1-UE (40.3 vs. 7.8%), and a lower rate of T3- and T4-stage cancer (41.9 vs. 15.9% and 10.1 vs. 7.7%, respectively) (p<0.01)." (PMID 23545944, 2013). "Based on these findings, we hypothesized that SCFAs induce CAPZA1-overexpressing cell production in H pylori–infected gastric mucosa, leading to CD44v9-positive cancer stem-like cell development through stabilization of CagA in CAPZA1-overexpressing cells." (PMID 41586340, 2026). "Notably, CAPZA1 demonstrates strong immunoreactivity in malignant colorectal cells compared to normal cells, consistent with findings in cancer patient-derived tissues." (PMID 39234565, 2024). "CAPZA1 mRNA levels from 33 cancer types in the TCGA were applied to TIMER." (PMID 36686785, 2022).
cancer (continued). "Our GO enrichment revealed that RPL22L1, INHBA, and CAPZA1 had a significantly higher expression levels in MSI than in MSS, and these genes were also upregulated in CRC cancer tissues compared with their levels in matched normal tissues." (PMID 35909892, 2022). "INHBA, RPL22L1, CAPZA1, and HMGCS2 showed significant differential levels in dMMR/MSI cancer tissues and were finally selected for further detection." (PMID 35909892, 2022). "Among them, F-actin-capping protein subunit alpha-1 (CAPZA1) has recently been related to the migratory and invasive abilities of cancer cells." (PMID 33777788, 2021). "Moreover, several studies have shown that the intercellular adhesion‐related molecules such as E‐cadherin, ZO‐1, CAPZA1, and SCIN can impact the prognosis of cancer patients." (PMID 31989722, 2020).
infection (3 papers, 2016 to 2026). The state of being infected such as from the introduction of a foreign agent such as serum, vaccine, antigenic substance or organism. "In 3 independent western blot analyses (P<0.05), as shown in, compared with the H1N1pdm09 infection, the down- or up-regulated proteins of CAPZA1 (33KDa), OAT (49KDa), PCBP1 (37KDa), EIF5A (18KDa), PAFAH1B2 (26KDa) in H7N9 infection were consistent with the 2-D DIGE results." (PMID 27223893, 2016). "In contrast, H pylori infection under presence of But significantly increased CD44v9-positive cell populations in both corpus and antrum-derived mucosoids within strong CAPZA1 staining, but not H pylori ΔcagPAI infection." (PMID 41586340, 2026). "In contrast, infection with the H pylori ΔcagPAI strains under the same conditions resulted in no detectable CD44v9-positive cells, despite strong CAPZA1 staining." (PMID 41586340, 2026).
CAPZA1 also shares sentences with these, for which no sentence is quoted: malignant melanoma (2 papers); cardiovascular disease (1); colon adenocarcinoma (1); echovirus infection (1); epithelioid sarcoma (1); infertile (1); lipodystrophy (1); metabolic disorders (1); metabolic syndrome (1); neuroblastoma (1); preeclampsia (1); stomach adenocarcinoma (1).